RTN4RL1 (reticulon 4 receptor like 1)
Description:
Cell surface receptor. Plays a functionally redundant role in postnatal brain development and in regulating axon regeneration in the adult central nervous system. Contributes to normal axon migration across the brain midline and normal formation of the corpus callosum. Protects motoneurons against apoptosis; protection against apoptosis is probably mediated by MAG. Plays a role in inhibiting neurite outgrowth and axon regeneration via its binding to neuronal chondroitin sulfate proteoglycans. Binds heparin (By similarity). Like other family members, plays a role in restricting the number dendritic spines and the number of synapses that are formed during brain development. Signaling mediates activation of Rho and downstream reorganization of the actin cytoskeleton.
Synonyms: NgR3; NGRH2; DKFZp547J144
Tractability: Small molecule: it belongs to a druggable protein family. Antibody: UniProt places it where antibodies can reach, with high confidence; its Gene Ontology location is reachable by antibodies, with high confidence; UniProt predicts a signal peptide or a membrane-spanning region. PROTAC: ubiquitination databases record sites on it.
Gene: Protein-coding gene on chromosome 17 (1,934,677 to 2,025,334, reverse strand). Ensembl gene ENSG00000185924.
Subcellular location: Cell membrane; Membrane raft; Perikaryon; Cell projection
Subcellular location (Human Protein Atlas): Actin filaments; Midbody; Nucleoplasm; Plasma membrane
Pathways (Reactome):
Metabolism of proteins: Post-translational modification: synthesis of GPI-anchored proteins
Gene Ontology:
Molecular function: protein binding; signaling receptor activity; chondroitin sulfate binding; heparin binding
Biological process: axon regeneration; negative regulation of axon regeneration; negative regulation of neuron projection development; positive regulation of synapse assembly; corpus callosum development
Cellular component: cell surface; extracellular exosome; membrane raft; plasma membrane; extracellular region; perikaryon
Genetic constraint (gnomAD): Loss-of-function variants: 7 observed, 21 expected, observed/expected ratio (o/e) 0.33, 90% interval 0.19 to 0.63. The upper end of that interval is the gene's LOEUF score, 0.63, which puts it in group 2 of 6, group 1 being the genes least tolerant of losing a copy. Missense variants: 500 observed, 582.56 expected, observed/expected ratio (o/e) 0.86, 90% interval 0.8 to 0.92. Synonymous variants: 297 observed, 275.77 expected, observed/expected ratio (o/e) 1.08, 90% interval 0.98 to 1.19.
Homologues: Orthologues: chimpanzee RTN4RL1 (99% identical), macaque RTN4RL1 (98% identical), guinea pig RTN4RL1 (90% identical), pig RTN4RL1 (90% identical), dog RTN4RL1 (90% identical), rabbit RTN4RL1 (89% identical), mouse Rtn4rl1 (89% identical), rat Rtn4rl1 (87% identical), tropical clawed frog rtn4rl1 (68% identical), zebrafish rtn4rl1b (57% identical), zebrafish rtn4rl1a (52% identical). Paralogues in human: RTN4RL2 (44% identical), RTN4R (41% identical), FLRT3 (25% identical), FLRT2 (23% identical), NYX (23% identical), FLRT1 (23% identical), LRRC15 (23% identical), LRRC4B (23% identical), LRRC4C (22% identical), LRRTM4 (22% identical), LRRC4 (22% identical), LRRTM3 (20% identical), and 10 more.
Diseases named in the same sentence as RTN4RL1 in open-access papers:
RTN4RL1 is named in the same sentence as 17 diseases in open-access papers, as found by Europe PMC text mining. Sharing a sentence is not in itself a finding about the gene and the disease. The quoted sentences say what the papers report.
diabetes (1 paper, 2020). "This implies that the effects of RTN4RL1 on BMI may be secondary to its main effect on diabetes." (PMID 31888951, 2020).
endometriosis (1 paper, 2016). The growth of functional endometrial tissue in anatomic sites outside the uterine body. "Since the rare marker in RTN4RL1 on chromosome 17 is absent from Danes, we searched for additional evidence for its association with endometriosis in the Icelandic samples." (PMID 27453397, 2016).
omphalocele (1 paper, 2025). Omphalocele is an embryopathy classified in the group of abdominal celosomias and is characterized by a large hernia of the abdominal wall, centered on the umbilical cord, in which the protruding viscera are protected by a sac. "The findings of this study indicate that PAFAH1B1, YWHAE and CRK are associated with major phenotypes of 17p13.3, and RTN4RL1 may be involved in white matter changes and HIC1 might contribute to the occurrence of omphalocele." (PMID 40390087, 2025). "While PAFAH1B1, YWHAE and CRK are associated with major phenotypes of 17p13.3, RTN4RL1 may be involved in white matter changes and HIC1 might contribute to the occurrence of omphalocele." (PMID 40390087, 2025).
osteosarcoma (1 paper, 2024). A usually aggressive malignant bone-forming mesenchymal neoplasm, predominantly affecting adolescents and young adults. "Compared to the sham group, the SNL group had higher gene expression levels of Gadd45g (growth arrest and DNA-damage-inducible 45 gamma) and Fos (FBJ osteosarcoma oncogene), while it had lower gene expression levels of Igf1, Ccl2, Hdac2, Rtn4rl1, Nfkb2, Gpr84, Pik3cg, and Abcc8." (PMID 38790607, 2024).
RTN4RL1 also shares sentences with these, for which no sentence is quoted: schizophrenia (2 papers); tumor (2); bronchial hyperreactivity (1); cancer (1); Cognitive impairment (1); congenital heart disease (1); demyelination (1); infection (1); Leukoencephalopathy (1); major depressive disorder (1); medulloblastoma (1); microcephaly (1); Mild intellectual disability (1).